DES (desmin)
Diseases named in the same sentence as DES in open-access papers (continued):
Sharing a sentence is not in itself a finding about the gene and the disease.
cardiomyopathy (continued). "Thus, future gene therapy approaches for the cure of cardiomyopathy in desminopathies that are based on the overexpression of WT desmin appear particularly useful for patients with a complete lack of desmin protein." (PMID 32322014, 2019). "Cell transfection experiments, as well as analysis of recombinant mutant desmin, have revealed an abnormal aggregation which indicates that the formation of a “poison protein” might be involved in DES-associated cardiomyopathies." (PMID 31718026, 2019). "The R120G mutation results in an irregular protein structure and defective chaperone-like function, which may accelerate the accumulation of desmin aggregation, thereby leading to desmin-related myopathy and also early onset of cardiomyopathy." (PMID 28484965, 2017). "Overexpression studies of mutant desmin I451M and R454W in C2C12 myoblasts show that both mutants can be readily incorporated into the endogenous IF networks; however, in humans, they cause severe cardiomyopathy and skeletal muscle disease." (PMID 28470624, 2017). "Finally, it introduces Nkx2.5 as an additional factor potentially contributing to the worsening of the desmin knockout heart defects with increasing age and of human desmin related cardiomyopathies." (PMID 26787680, 2016). "Numerous sarcomeric components/cytoskeletal proteins were identified as showing increased synthesis in our pSILAC experiments, several of which play important roles in cardiac function and/or in cardiomyopathies (e.g. desmin, vinculin, NRAP (nebulin-related anchoring protein) and Lmod)." (PMID 27512079, 2016). "Similarly, cardiac assessment in both HET and HOM R349P desmin knock-in mice revealed a combined picture of cardiomyopathy, conduction defects and arrhythmias." (PMID 25394388, 2015). "Therefore, we conclude that HD mouse models develop an interstitial type fibrosis and are free from the fibrotic patches that can be observed in desmin-related cardiomyopathy." (PMID 25101683, 2014). "Desmin is intimately involved in mitochondrial positioning and homeostasis and mitochondrial changes are a prominent associated phenotype in both DRM patients and mouse models of cardiomyopathy." (PMID 23530264, 2013). "Notably, and subject of this review, mutations of desmin, the major class III IF protein in striated and smooth muscle cells, causes progressive myopathy, cardiomyopathy, cardiac conduction defects, and arrhythmias." (PMID 23143191, 2013). "Indeed, preventing aggregate formation has been suggested as the mode by which HSPB8 can prevents desmin-related cardiomyopathy." (PMID 21731611, 2011). "In one of these loci where SigNet and PoPS differ, both selected genes may be causal: at the locus where SigNet selects SLC4A3, responsible for a Mendelian form of short QT syndrome, PoPS selects DES (desmin), responsible for a Mendelian form of cardiomyopathy." (PMID 39774334, 2025). "Indeed, although desmin is not essential since desmin deficient or knockout mice are viable, these mice develop myopathies, especially cardiomyopathies, early in their lifetime." (PMID 37760006, 2023). "Moreover, desmin aggregation leads to cardiomyopathy phenotypes." (PMID 36158202, 2022). "Furthermore, desmin dysfunction is also linked to cardiomyopathy without being directly linked to a specific desmin mutation." (PMID 35159226, 2022). "Clinically relevant mouse models of cardiac proteotoxicity, such as the mutant desmin transgenic mouse with 7-amino acid deletion R172-E178 in desmin (D7-Des Tg), display a collapse of the desmin network and an accumulation of desmin aggregates that contributes to the development of cardiomyopathy." (PMID 32982788, 2020). "For example, the presence of congenital heart disease could possibly be ascribed to the deregulation of the DES, LDB3, POPDC2 and SLC4A3 genes, all of which have previously been associated with cardiac function and pathology, such as cardiomyopathy." (PMID 23816241, 2013).
cardiomyopathy (continued). "Indeed, the desmin mutant R406W-desmin, which causes severe myopathies and cardiomyopathies in humans, was characterized to assemble not much beyond the ULF state when assembly was conducted in 50 mM sodium chloride, a condition where wild-type desmin rapidly forms very long filaments." (PMID 36101505, 2022). "In contrast, the cardiological workup demonstrated all three desmin-related cardiac disease manifestations in HET and HOM mice, i.e., true cardiomyopathy, conduction defects, and arrhythmias." (PMID 25394388, 2015). "In the context of a mouse model for tumor necrosis factor alpha-induced cardiomyopathy, it was found that increased expression of TNF-alpha leads to degradation and changes in the subcellular distribution of desmin and to pathological aggregate formation." (PMID 23143191, 2013). "Increased filamentous desmin appears to be protective in mdx mouse hearts and may modulate the severity of DMD cardiomyopathy." (PMID 41163301, 2025). "CRYABD109G results in the development of desmin-related cardiomyopathy because the mutant CRYAB is no longer able to efficiently stabilize and prevent the aggregation of desmin filaments." (PMID 38474073, 2024). "The analysis of p62-positive aggregates in the myocardium showed a high prevalence of diffused p62-positive aggregates in phospholamban (PNL) and desmin-related (DRC) cardiomyopathy patients, confirming earlier findings in a mouse model of DRC desmin mutant and impaired lysosomal function." (PMID 37176163, 2023). "Corresponding data derived from patients with a desmin knock-out cardiomyopathy have not yet been published." (PMID 36233322, 2022). "The cardiac phenotype in these mice mimicked desmin-related cardiomyopathies; even though desmin was not directly involved, protein aggregates containing Myozap and other intercalated disc (ID) proteins, such as desmoplakin, were present." (PMID 34899865, 2021). "In contrast, our sedentary laboratory mice, although they clearly display desmin-positive protein aggregation pathology and develop a cardiomyopathy, do neither develop skeletal muscle weakness nor marked myopathological changes." (PMID 27393313, 2016). "Although both aggregate formation and disturbed autophagy are well-known characteristics of desmin-related myopathies and cardiomyopathies, knowledge has been lacking regarding the role of autophagy in the molecular pathogenesis of desmin-related muscle pathology and aggregate formation." (PMID 37277577, 2023). "However, the association between damage of the cardiac contractile unit—desmin and neighboring sarcomere—and the iNOS/mTOR/TIMP-1/collagen axis of fibrosis in rats with T2DM-induced cardiomyopathy has not been previously investigated." (PMID 35625721, 2022). "The mechanism by which desmin IFs contribute to the maintenance of healthy muscle and the mechanism by which lack of desmin leads to cardiomyopathy remain unclear." (PMID 34285704, 2021). "The deleterious effects of abnormal desmin IF networks, due to either the additional presence of mutant or the complete lack of wild type desmin protein, are emphasized by the group of human desminopathies that comprise autosomal-dominant and recessively inherited myopathies and cardiomyopathies." (PMID 32752098, 2020). "Other mouse models of cardiomyopathy that have not genetically targeted desmin or CRYAB expression see changes in desmin distribution and its inclusion into aggregates and an association with CRYAB." (PMID 23530264, 2013).
leiomyosarcoma (109 papers, 2006 to 2026). An uncommon, aggressive malignant smooth muscle neoplasm, usually occurring in post-menopausal women. "Intra-abdominal synovial sarcoma, either primary or metastatic, with unusual desmin positivity raises the diagnostic challenge, since a wide range of differential diagnoses could show a similar immunophenotype (leiomyosarcoma, desmoid tumor, myofibroblastic tumor, and rarely GIST etc.)." (PMID 22966471, 2012). "An excisional biopsy was performed; pathology revealed a highly cellular proliferation of fusiform cells with eosinophilic cytoplasm that stained positively with smooth muscle actin and desmin, consistent with leiomyosarcoma." (PMID 41551622, 2026). "Biopsy of one of the femoral vein masses showed a high-grade spindle cell neoplasm positive for SMSA and desmin, consistent with leiomyosarcoma." (PMID 41380714, 2026). "Histopathological examination confirmed the diagnosis of leiomyosarcoma, with immunohistochemical positivity for α-smooth muscle actin, desmin, and h-caldesmon." (PMID 40840074, 2025). "We reported a case of DDLPS with leiomyosarcoma-like features showing strong expression of myoid markers such as h-caldesmon, desmin, and α-SMA." (PMID 41333224, 2025). "Staining with desmin can be detected in rhabdomyosarcoma or leiomyosarcoma, while CD99, p40, or pankeratin staining is seen in Ewing sarcoma." (PMID 39420880, 2024). "Immunohistochemical staining positive for at least two of the following markers is suggestive of a diagnosis of leiomyosarcoma, which includes desmin, smooth muscle actin, muscle actin HHF-35, h-caldesmon, smooth muscle myosin, or calponin." (PMID 39411630, 2024). "Smooth muscle actin, desmin, and caldesmon are positive immunohistochemical markers of smooth muscle cells seen in both leiomyomas and leiomyosarcomas." (PMID 39081688, 2024). "Leiomyosarcoma can be differentiated from other soft tissue sarcomas by the presence of smooth muscle cell actin and desmin on immunohistochemistry." (PMID 39086921, 2024). "The tumors are definitively diagnosed with histopathology and immunohistochemistry, with leiomyosarcoma showing actin and desmin positive reactivity consistent with smooth muscle cell origin and CD117, CD34, PDGFRA, and DOG1 negativity." (PMID 38915340, 2024). "Histopathological features as well as the immunohistochemical results, positive for vimentin, actin, myosin and desmin, confirmed the mesenchymal origin and the myoid phenotype of both testicular tumours supporting the diagnoses of leiomyosarcoma." (PMID 37525233, 2023). "Anti‐desmin staining is found in 47–85% of superficial leiomyosarcomas and is less common in higher‐grade tumors." (PMID 35228875, 2022). "The IHC results of DDL with well-differentiated leiomyosarcoma-like area (case 33) exhibited positivity for smooth muscle actin, desmin and h-caldesmon." (PMID 36059611, 2022). "Additional immunohistochemical analysis using antibodies against smooth muscle actin, desmin, and CD-117 demonstrated that the mass was consistent with a leiomyosarcoma." (PMID 35211538, 2022). "Immunohistochemical staining of deparaffinized sections shows expression of desmin‐ and muscle‐specific actin in the great majority of leiomyosarcomas." (PMID 35228875, 2022). "By contrast, leiomyosarcoma is usually positive for smooth muscle cell markers such as actin, desmin, and h-caldesmon." (PMID 34143361, 2021). "Immunohistochemical staining shows an expression of SMA, muscle-specific actin, and desmin in most leiomyosarcomas, and expression of S-100 protein, CD34, Ki-67, myogenin, and cytokeratin has also been reported in some cases." (PMID 34544483, 2021). "Smooth muscle tumors such as leiomyoma and leiomyosarcomas show strong positivity for actin and desmin and negativity for S100, BCL2, and CD34." (PMID 34211794, 2021). "In general, leiomyosarcoma shows strong positivity for smooth muscle actin and desmin and negativity for cytokeratin and S100." (PMID 31632881, 2019).
leiomyosarcoma (continued). "CD117 and CD34 are positive in GIST and muscle-specific proteins, such as actin, Desmin and caldesmon are positive in smooth muscle tumors such as leiomyoma and leiomyosarcoma." (PMID 30710876, 2019). "The most distinctive histopathological characteristics of leiomyosarcomas are presence of coagulative tumour cell necrosis, cytological atypia, high mitotic rate and positive staining for muscle markers (actine, desmin, caldesmon)." (PMID 28747229, 2017). "Leiomyomas and leiomyosarcomas have more abundant eosinophilic cytoplasm and larger nuclei, and a majority will express at least one muscle marker (usually smooth muscle actin or desmin)." (PMID 27672467, 2016). "Usually, leiomyosarcoma stains positive for vimentin and smooth muscle actin, and they typically express desmin." (PMID 27580598, 2016). "Immunohistochemichal stains for leiomyosarcoma were positive in that desmin and smooth muscle actin were weakly positive, and vimentin was strongly positive." (PMID 26640482, 2015). "Immunohistochemical staining was positive for desmin and smooth muscle actin which supported a diagnosis of leiomyosarcoma." (PMID 26640482, 2015). "Leiomyosarcoma and gastrointestinal stromal tumors will be positive for at least one of the myogenic immunohistochemical stains (usually smooth muscle actin or desmin), while endometrial stromal sarcoma will be immunoreactive for the estrogen receptor." (PMID 25114818, 2014). "The immunohistochemical profile of a leiomyosarcoma will reveal characteristics of smooth muscle differentiation including expression of smooth muscle actin and muscle specific actin and desmin." (PMID 24744951, 2014). "Leiomyoma and leiomyosarcoma are tumors which express smooth muscle cell markers, including desmin, α-smooth muscle actin, and h-caldesmon, but they are negative for beta-catenin." (PMID 25349618, 2014). "The pathognomonic findings of leiomyosarcoma are spindle-shaped tumor cells with positive markers for smooth muscle cells, vimentin, muscle actin, alpha-smooth muscle actin, and desmin." (PMID 23509466, 2013). "Smooth muscle actin, desmin, and myoglobin D1 can be used to establish the diagnoses of leiomyosarcoma, rhabdomyosarcoma." (PMID 23082265, 2012). "Leiomyosarcomas arise from the smooth muscle, are spindle cell shaped and stain for desmin and actin." (PMID 17603895, 2007). "This view was based largely on the fact that the tumors looked like classic leiomyosarcomas with spindled and epithelioid areas, and stained with desmin." (PMID 18053181, 2007). "Finally, leiomyosarcoma stains positively for both smooth muscle actin and desmin, confirming muscular origin." (PMID 41551622, 2026). "The negative reactivity of tumor cells for other lineage-specific markers, such as cytokeratin AE1/AE3, S100 protein, CD34, and SMA/desmin, allows distinction from poorly differentiated squamous cell carcinoma, melanoma, angiosarcoma, and leiomyosarcoma, respectively." (PMID 39449379, 2024). "Furthermore, leiomyomas and leiomyosarcomas typically exhibit diffuse and strong positive expression of smooth muscle actin and desmin, aiding in differential diagnosis." (PMID 39896188, 2024). "From a histological perspective, both GISTs and leiomyosarcomas share similar features, so a definitive diagnosis relies on immunohistochemical data: a vast majority of GISTs express c-KIT protein (CD117) and CD34, whereas leiomyosarcomas often express desmin and smooth muscle actin." (PMID 37395913, 2023). "Further, although occasional leiomyosarcomas are immunoreactive for S100β, this tumor was negative for desmin, which ruled out this diagnostic possibility." (PMID 33707600, 2021). "SCRMS may resemble fibrosarcoma or leiomyosarcoma, making desmin and myogenin and myoD1 stains important parts of the workup of infantile fibrosarcomatous lesions." (PMID 30613391, 2018).
leiomyosarcoma (continued). "Characteristically, a leiomyosarcoma shows positive staining for smooth muscle actin and desmin, as also demonstrated in the present case, and may be properly diagnosed when relevant immunohistochemistry (IHC) is employed." (PMID 27631424, 2016). "Leiomyosarcoma are usually positive for desmin and smooth muscle actin." (PMID 25253623, 2014). "In Fletchers’ 1992 retrospective review he used diagnostic criteria for leiomyosarcoma that included, co-expression of desmin and actin with myoglobin negativity and an absence of cross striations." (PMID 24216705, 2013). "Leiomyoma and leiomyosarcoma were excluded based on the negativity of tumour cells to desmin." (PMID 22966474, 2012). "Histopathology of leiomyosarcoma reveals spindle tumor cells, which are positive for markers of smooth muscle activity including vimentin, muscle actin, alpha-smooth muscle actin, and desmin." (PMID 20178598, 2010). "Key immunohistochemical markers aid in distinguishing these tumors: GISTs are typically positive for CD117 and DOG-1, while leiomyomas and leiomyosarcomas express smooth muscle actin (SMA) and desmin but lack CD117." (PMID 40282558, 2025). "In contrast, leiomyomas and leiomyosarcomas typically lack CD117 and DOG1 expression, but are positive for smooth-muscle markers such as SMA and desmin, while schwannomas exhibit strong S100 expression with negativity for both markers." (PMID 41465833, 2025). "These tumors can differentiate from other subepithelial lesions, including leiomyoma, leiomyosarcoma, GI cysts, and lipoma; through IHC by the positiveness of CD117 and KIT negativeness of Desmin and S100." (PMID 35658308, 2022). "Leiomyosarcomas have blunt-ended, cigar-shaped nuclei, brightly eosinophilic cytoplasm, and are positive for SMA, caldesmon, and desmin." (PMID 32867125, 2020). "Leiomyosarcoma, RMS and Wilms tumors contain the intermediate filament protein desmin present in muscle." (PMID 30973903, 2019). "Immunohistochemically, leiomyosarcomas are almost invariably strongly positive for SMA, and desmin is usually positive (70–80%), along with positivity for heavy-caldesmon and smooth muscle myosin." (PMID 30271265, 2018). "The present study describes a case of a mixed-type mesenteric liposarcoma with areas of dedifferentiation and the features of a leiomyosarcoma, including IHC positivity for SMA and desmin." (PMID 24348818, 2014). "The liposarcoma was also positive for desmin and smooth muscle actin (SMA), which was consistent with the features of a leiomyosarcoma." (PMID 24348818, 2014). "Expression was negative for CD34, CD117, S-100, and desmin, which excluded a gastrointestinal stromal tumor, schwannoma, leiomyoma, and leiomyosarcoma, respectively." (PMID 39278889, 2025). "Desmin, Myf4, and H‐caldesmon reactions were all completely negative, excluding the possibility of rhabdomyosarcoma and leiomyosarcoma." (PMID 40522461, 2025). "In our case, the biopsy was positive for SMA and desmin, negative for other markers leading to the conclusion that the tumor was a leiomyosarcoma." (PMID 40098841, 2025). "The majority of soft-tissue sarcomas were myosarcomas – primarily leiomyosarcomas that were confirmed by positive desmin staining and negative myogenin staining, and rhabdomyosarcomas confirmed by positive desmin and negative myogenin staining." (PMID 41381412, 2025). "The pathology report labeled the specimen as an atypical smooth muscle neoplasm, positive for smooth muscle actin (SMA) and desmin and negative for S100 and Mart 1, consistent with metastatic leiomyosarcoma." (PMID 40098841, 2025). "In contrast, our case was negative for myogenic markers such as desmin, caldesmon, calponin, and MyoD1, as well as for the IMT-associated marker ALK, supporting the exclusion of leiomyosarcoma, rhabdomyosarcoma and IMT." (PMID 40936706, 2025). "In contrast, leiomyosarcoma is negative for KIT mutations and mostly positive for desmin, SMA, h-caldesmon, and vimentin." (PMID 38993816, 2024).